INS (insulin)
Diseases named in the same sentence as INS in open-access papers (continued):
Sharing a sentence is not in itself a finding about the gene and the disease.
diabetes (continued). "Diabetes Mellitus (DM) is a chronic, degenerative endocrine disease characterized by the decreased secretion of insulin by the pancreas (type 1 DM) or increased insulin resistance by the body’s cells (type 2 DM), increasing blood glucose levels." (PMID 35739932, 2022). "Even though type 2 diabetes mellitus (T2DM) represents a worldwide chronic health issue that affects about 462 million people, specific underlying determinants of insulin resistance (IR) and impaired insulin secretion are still unknown." (PMID 35620114, 2022). "Diabetes mellitus (DM) is a widespread, clinically heterogeneous disease characterized by a chronic increase in blood glucose levels due to impaired insulin secretion and/or peripheral insulin resistance 20-23." (PMID 34976197, 2022). "Diabetes mellitus (DM) is a rapidly growing global health issue, which is a result of a problem with insulin secretion or its effect on the body." (PMID 36277526, 2022). "However, in the contemporary context, diabetes education has shifted away from set food intake and insulin dosages to allow for greater flexibility and freedom of food choice in line with the increased availability of insulin products with variable profiles." (PMID 35745190, 2022). "In diabetes, high levels and stores of iron in the body may result in a selective damage of the pancreatic beta-cells through excessive oxidative stress, which then leads to impaired insulin synthesis and release." (PMID 36235661, 2022). "Thus, giving us insights into how INS deficits can contribute to neonatal diabetes." (PMID 35563490, 2022). "Both pancreatic endocrine (i.e. production of hormones such as insulin or glucagon) and exocrine (i.e. production of enzymes to aid digestion and subsequent nutrient absorption) functions are critical for nutritional metabolism and chronic diseases including diabetes." (PMID 35504844, 2022). "STZ induces diabetes by depleting insulin production due to pancreatic β-cell destruction rather than by impairing insulin sensitivity; this may explain the lack of a hypoglycemic effect of iron deprivation in this model of diabetes." (PMID 35453417, 2022). "Besides, about 24.6% were on oral anti-diabetes drugs plus insulin at the same time." (PMID 36028845, 2022). "Thus, this study was done to discover a new curing method for diabetes by producing cells that can release insulin and could survive under low oxygen circumstances, and assessing their healing ability against diabetes in rats." (PMID 36248064, 2022). "Individuals with longer duration of diabetes were more likely to increase their insulin carbohydrate ratio on the competitive race day than on the non-competitive training day while the reverse was true for those with a shorter duration of diabetes with T1D (r = -0.57, p = 0.05)." (PMID 36992757, 2022). "Therefore, these “Hub cells” are essential for regulating synchronization of islet insulin secretion and any disruption of it could contribute to diabetes onset." (PMID 35185804, 2022). "Although previous studies showed that POA treatment of diabetes mellitus has the beneficial effect of lowering blood glucose or lipid levels, it has also been shown to increase vasoconstriction, especially under the high glucose and high insulin conditions in this study." (PMID 35436932, 2022). "Furthermore, flies can achieve homeostasis via the insulin signalling pathway, Drosophila with InR defects (insulin receptor mutant) showed significantly lower insulin tolerance, and they can serve as a screening model for potential probiotic foods for diabetes management." (PMID 35830425, 2022). "Diabetes mellitus (DM) is a debilitating, long-term disease that arises when the body is unable to produce enough insulin or is unable to use the insulin produced efficiently." (PMID 36678531, 2022).
diabetes (continued). "This may be attributed to the cytotoxicity of STZ that leads to rapid β-cell failure or elevated levels of leptin and adiponectin in diabetic rats, which mimics the pathophysiology of lean diabetes patients with severe insulin secretion defects compared with individuals with obesity." (PMID 36613966, 2022). "A total of 399 patients had DM (49.9%), and of those patients, 338 (84.7%) patients had type 2 diabetes and 164 of these DM patients (41.1%) were on insulin therapy." (PMID 35755551, 2022). "Diabetes mellitus (DM) is a group of metabolic disorder that is characterized by high blood sugar levels due to the body’s inability to produce or use insulin." (PMID 37529091, 2022). "Alloxan induces diabetes through intracellular generation of ROS, with subsequent increases in cytosolic calcium level and thus oxidative pressure through reduction of endogenous anti-oxidation mechanisms following the suppression of insulin release and synthesis." (PMID 36588726, 2022). "Background and objective: Diabetes mellitus (DM) refers to a group of metabolic disorders characterized by hyperglycemia resulting from impaired secretion or action of insulin." (PMID 35207724, 2022). "Given our results, one can also argue that diets such as LCHF, which lowers both average insulin and glucose levels, may be beneficial for treating diabetes and cardiovascular diseases, and short-term clinical studies indicate that LCHF does indeed lower fat levels in both the liver and blood." (PMID 36094958, 2022). "Type 2 diabetes mellitus (T2DM) is a chronic, complex metabolic disease characterized by chronic hyperglycemia causing from insufficient insulin signaling because of insulin resistance or defective insulin secretion, and may induce severe complications and premature death." (PMID 35614469, 2022). "Diabetes mellitus (DM) is a chronic disease due to impaired insulin secretion or insulin resistance or both." (PMID 36004341, 2022). "Additionally, higher BDNF methylation was associated with high fasting insulin levels, supporting the hypothesis that BDNF methylation plays important role in diabetes progression." (PMID 35225959, 2022). "Considering that patients under insulin medication could have greater diabetes severity (resulting in more severe hyperglycemia and putting them at a higher risk of perioperative stroke), a subgroup analysis stratified by preoperative insulin medication was conducted." (PMID 36337712, 2022). "Thus, there likely exists bidirectional exocrine-endocrine crosstalk amidst a shared milieu of pro-inflammatory and growth signals, including insulin itself, that may drive both neoplastic transformation and β-cell dysfunction in diabetes." (PMID 35813631, 2022). "The Diabetes Epidemiology: Collaborative analysis Of Diagnostic criteria in Europe (the DECODE) and in Asia (the DECODA) studies from the World Health Organization (WHO) demonstrated that both insulin resistance and secretion capacity are higher in Caucasians than Asians27–29." (PMID 35332212, 2022). "A 55-year-old woman with a 20-year history of type 2 diabetes mellitus (DM) was treated with basal-bolus insulin and oral hypoglycemic agents." (PMID 36309669, 2022). "Diabetes patients receiving insulin may experience rates as high as 25% of the general population." (PMID 35619856, 2022). "In the 50 years since this discovery, we have seen a remarkable evolution in diabetes care, with further refinements of injectable analogues to produce more consistent basal insulin levels as well as faster acting insulin analogues that more closely mimic prandial insulin release." (PMID 36251572, 2022). "Indeed, the addition of quinoa to the habitual diet significantly affected anthropometric parameters (body weight, waist circumference, and fat mass) as well as fasting insulin and blood lipid concentrations in individuals with overweight obesity or pre-diabetes." (PMID 36118764, 2022).
diabetes (continued). "However, it is still unclear whether an oleic acid-activated molecular mechanism is the most important for preventing insulin resistance, and there are still open questions regarding the effects of oleic acid on diabetes in humans." (PMID 36685282, 2022). "Diabetes Mellitus (DM) is a very common chronic metabolic disease characterized by the absence or ineffectiveness of insulin." (PMID 35331657, 2022). "Thus, overall glycerol intake may have an underrecognized impact on prandial glucose levels, particularly in patients with diabetes who take mealtime insulin for glucose control." (PMID 36295792, 2022). "In addition to the benefits of insulin for diabetes treatment, it is suggested that regular monitoring of insulin levels and screening and treatment for subclinical insulinemia may be an efficient colorectal and endometrial cancer prevention strategy." (PMID 35530326, 2022). "The transition between pre-diabetes and early-stage T2D can be difficult to catch in a standard clinical setting and is, at this early stage, reversible, with pancreatic beta-cells initially able to compensate for insulin resistance by increasing the amount and duration of insulin secretion." (PMID 36291702, 2022). "Moreover, individuals with type 1 diabetes are more commonly treated with insulin, thus trained to have more advanced diabetes numeracy skills such as interpreting blood glucose meter data, administering medication dosages, and following specific nutritional recommendations." (PMID 36078271, 2022). "For example, insulin needs of a patient may vary based on nutritional status, renal function, steroid use, the severity and nature of the illness that resulted in the hospital admission, and the type of diabetes." (PMID 35917098, 2022). "Experiments have shown that mice with pancreatic β‐cells lacking Hdac3 displayed decreased pancreatic insulin content and disrupted glucose‐stimulated insulin secretion, with intermittent spontaneous diabetes and enhanced susceptibility to STZ‐induced diabetes." (PMID 34984701, 2022). "Type 2 diabetes, the most common type of DM, highly correlates with progressive β-cell failure, which manifests as combined insulin secretory dysfunction and insulin resistance." (PMID 36034435, 2022). "In patients with diabetes, impaired insulin signalling might lead to chronic subclinical low-grade inflammation via activation of AP-1 and NF-κB leading to a decrease in anti-inflammatory cytokines and to an increase in the pro-inflammatory cytokines TNF-α, IL-6 and IL-1β." (PMID 35253006, 2022). "Furthermore, the study investigated whether proxies of impaired beta cell function—insulin treatment during GDM pregnancy and development of manifest diabetes mellitus—influence incident CVMM risk." (PMID 36085031, 2022). "Moreover, she had diabetes mellitus type 1 and was receiving insulin." (PMID 35999988, 2022). "Diabetes mellitus (DM) is the most common chronic metabolic disorder characterized by hyperglycaemia due to impaired insulin secretion or increased insulin resistance." (PMID 34955676, 2022). "Diabetes mellitus (DM) is a chronic metabolic disease characterized by hyperglycemia due to impairments in either insulin secretion and / or insulin effect." (PMID 35624486, 2022). "Also, a study that induced both hypercholesterolemia and diabetes in the same animals showed that extract of purslane leaves (1 gr per 100 gr diet, 28 days) could decrease blood glucose and HbA1C, and increase insulin levels." (PMID 36474567, 2022). "The Insulin Resistance Intervention after Stroke (IRIS) trial which involved 3876 patients, demonstrated that pioglitazone, an insulin-sensitizer, reduced the risk of recurrent stroke and myocardial infarction in patients without diabetes who had recent ischemic stroke or TIA11." (PMID 35102177, 2022).
diabetes (continued). "In addition, insulin use was calculated based only on the 1‐year baseline period and among the patients with diabetes who met the sample selection criteria, which may undercapture patients’ insulin use history." (PMID 35352855, 2022). "Single nucleotide polymorphisms (SNPs) in insulin and insulin receptor genes may influence the interaction between the two molecules, as may anti-insulin antibodies (IAs), commonly found in patients with type 1 diabetes mellitus (T1D) or type 2 diabetes mellitus (T2D) treated with exogenous insulin." (PMID 35742925, 2022). "Long-acting basal insulin analogues (insulin glargine U100, insulin detemir) significantly improved diabetes management, providing longer duration, flatter profiles of action, lower risk of hypoglycemia, and less glycemic variability compared to NPH (Neutral Protamine Hagedorn) insulin." (PMID 35802405, 2022). "The report from Diabetes epidemiology: collaborative analysis of diagnostic criteria I Europe (DECODE) and in Asia (DECODA) studies revealed a predominance of insulin resistance with obesity in T2D patients in Europe and US, whereas impaired insulin secretion is predominant in East Asia." (PMID 35351190, 2022). "Thus, γδ T cells recruited to the pancreas that respond to insulin peptides could also become specifically activated during the development of diabetes." (PMID 36291615, 2022). "Thus, protein synthesis (measured by incorporation of the non-metabolised amino-acid phenylalanine) in ribosomes from rat hearts is stimulated by insulin and inhibited by diabetes, and cardiac protein synthesis is increased by perfusion of rat hearts with insulin (see, for example,)." (PMID 35766350, 2022). "However, professional groups have issued statements advising healthcare providers against recommending DIY diabetes systems, and the FDA has warned against the use of unauthorized devices for diabetes management after a patient suffered an accidental insulin overdose." (PMID 36632334, 2022). "Diabetes mellitus (DM) is defined as a chronic and multifunctional metabolic disorder characterised by hyperglycaemia, resulting from impaired insulin secretion, insulin action or both." (PMID 35053127, 2022). "The occurrence of metabolic syndrome (MetS) significantly affects the course of diabetes mellitus (DM), resulting in deterioration of insulin sensitivity and metabolic control, as well as many cardiometabolic complications." (PMID 35745165, 2022). "Diabetes mellitus (DM) is a diverse group of chronic metabolic disorder which can result from a defect in insulin secretion, insulin action, or both." (PMID 36420434, 2022). "Diabetes mellitus (DM) is a chronic metabolic disease categorized by a prolonged rise in blood glucose levels due to a complete or partial failure of the insulin secretion process in the absorption mechanism." (PMID 35083086, 2022). "Diabetes mellitus [DM] is a disorder in which there is a markedly higher level of blood glucose due to insufficient insulin, β-cell dysfunction, insulin resistance, or both." (PMID 35625414, 2022). "Diabetes mellitus (DM), a complicated metabolic disorder, is due to insensitivity to insulin function or reduction in insulin secretion, which results in postprandial hyperglycemia." (PMID 35056163, 2022). "A Two-Step cluster analysis was performed on 1332 Chinese patients with diabetes based on six parameters (glutamate decarboxylase antibodies, age at disease onset, body mass index, glycosylated hemoglobin, homeostatic model assessment 2 to estimate β-cell function and insulin resistance)." (PMID 36457559, 2022). "Diabetes mellitus is a set of metabolic diseases characterized by hyperglycemia resulting from defects in pancreatic secretion or insulin resistance, resulting in a glucose metabolism imbalance that can lead to increased insulin production or decreased glucose uptake by insulin-dependent tissues." (PMID 35458674, 2022).
diabetes (continued). "However, the large difference between German and Norwegian Treatment scores from 2009 and 2017 (56.4 vs. 65.2) can support the nation that advances in diabetes treatment, such as the accessibility of insulin analogues and diabetes technology lead to better treatment related quality of life." (PMID 36387938, 2022). "EGCG may be beneficial in diabetes for increasing insulin sensitivity by suppressing inflammation." (PMID 35631180, 2022). "As it has been shown in diabetes, insulin may prove vital to T cell metabolism and regulation." (PMID 35711466, 2022). "Type 1 (insulin-dependent diabetes mellitus) is characterised by the close to total destruction of the β-cells of the pancreatic islets, while type 2 (non-insulin-dependent diabetes mellitus) is induced due to obesity, insulin resistance and/or impaired insulin secretion." (PMID 36295897, 2022). "Regarding mobile health applications, the majority of the patients with diabetes studied used them for blood glucose monitoring (93.4%), physical activity programs (44.3%) and nutritional programs (39.3%), and a few of them used applications for insulin dose determination (3.3%)." (PMID 35719798, 2022). "Additionally, it will be important to measure first-pass clearance of insulin by the liver directly, rather than metabolic clearance rate from clamps, to see if reduction in hepatic degradation of insulin is causative for diabetes." (PMID 35163746, 2022). "Diabetes mellitus (DM) is a general term for heterogeneous metabolic diseases characterized mainly by chronic hyperglycemia resulting from impaired action of insulin or impaired secretion of insulin or both." (PMID 36523699, 2022). "This increasing CGM slope prior to the competition may be influenced by the individual’s anxiety-proneness as measured by the STAI-trait survey, duration of diabetes, diabetes management as measured by HbA1c, and the insulin dosing behavior as measured by the ICII." (PMID 36992757, 2022). "Furthermore, in people with diabetes, insulin signaling is significantly affected by ROS." (PMID 35669072, 2022). "Additionally, the long-term diabetes-lowering medications taken by the donors might have a role in regulating HbA1c levels and enhancing insulin release." (PMID 36101450, 2022). "This proof-of-concept pilot study (ClinicalTrials.gov Identifier NCT03428932) examined whether MRI-derived indices of brain development and function and standardized IQ scores in adolescents with T1D could be improved with better diabetes control using a hybrid closed-loop insulin delivery system." (PMID 36042217, 2022). "Overall, patients suffering from diabetes can be categorized in three groups: Type 1 Diabetes Mellitus (T1D), where the body produces no or too little insulin; Type 2 Diabetes Mellitus (T2D), caused by an insulin resistance and Gestational Diabetes Mellitus (TGD) during pregnancy." (PMID 35062385, 2022). "Since diabetes mellitus research is considered as one of the fastest-growing fields of medicine, many different directional studies are performed every year to provide answers on how to restore the harmony in insulin status in the course of diabetes and in the diabetic milieu." (PMID 35454311, 2022). "The classification of diabetes mellitus, such as insulin deficient diabetes mellitus or mature onset of diabetes of the young could not be differentiated." (PMID 35558755, 2022). "Third, insulin injection is always the last resort for the treatment of T2DM in Taiwan and therefore, its use is always associated with a prolonged duration of diabetes and a more severe disease condition characterized by more diabetes complications and more complicated use of other medications." (PMID 35935880, 2022). "Complete understanding of the mechanisms underlying decreased tissue response to insulin action, as well as of the processes being crucially implicated in the preservation and recovery of beta cell mass would make diabetes no longer a chronic but a curable disease." (PMID 36246880, 2022).